ENSG00000285585 (novel protein)
Gene: Protein-coding gene on chromosome 3 (119,703,076 to 119,807,570, forward strand). Ensembl gene ENSG00000285585.
Genetic constraint (gnomAD): Loss-of-function variants: 62 observed, 67.83 expected, observed/expected ratio (o/e) 0.91, 90% interval 0.74 to 1.13. Missense variants: 719 observed, 728.57 expected, observed/expected ratio (o/e) 0.99, 90% interval 0.93 to 1.05. Synonymous variants: 247 observed, 258.73 expected, observed/expected ratio (o/e) 0.95, 90% interval 0.86 to 1.06.